GABRA1 (gamma-aminobutyric acid type A receptor subunit alpha1)
Description:
Alpha subunit of the heteropentameric ligand-gated chloride channel gated by Gamma-aminobutyric acid (GABA), a major inhibitory neurotransmitter in the brain. GABA-gated chloride channels, also named GABA(A) receptors (GABAAR), consist of five subunits arranged around a central pore and contain GABA active binding site(s) located at the alpha and beta subunit interface(s). When activated by GABA, GABAARs selectively allow the flow of chloride anions across the cell membrane down their electrochemical gradient. Alpha-1/GABRA1-containing GABAARs are largely synaptic (By similarity). Chloride influx into the postsynaptic neuron following GABAAR opening decreases the neuron ability to generate a new action potential, thereby reducing nerve transmission (By similarity). GABAARs containing alpha-1 and beta-2 or -3 subunits exhibit synaptogenic activity; the gamma-2 subunit being necessary but not sufficient to induce rapid synaptic contacts formation. GABAARs function also as histamine receptor where histamine binds at the interface of two neighboring beta subunits and potentiates GABA response (By similarity). GABAARs containing alpha, beta and epsilon subunits also permit spontaneous chloride channel activity while preserving the structural information required for GABA-gated openings (By similarity). Alpha-1-mediated plasticity in the orbitofrontal cortex regulates context-dependent action selection (By similarity). Together with rho subunits, may also control neuronal and glial GABAergic transmission in the cerebellum (By similarity).
Synonyms: EJM5; DEE19; ECA4; EIEE19; EJM
Tractability: Small molecule: an approved drug acts on it; a structure with a bound ligand is known; a high-quality ligand is known; it belongs to a druggable protein family. Antibody: UniProt places it where antibodies can reach, with high confidence; its Gene Ontology location is reachable by antibodies, with high confidence; UniProt predicts a signal peptide or a membrane-spanning region; the Human Protein Atlas places it where antibodies can reach. PROTAC: its protein half-life has been measured; a small molecule that binds it is known.
Target class: Ion channel; GABA-A receptor; Ligand-gated ion channel
Safety:
Unwanted effects reported when the protein is acted on. In parentheses: how it was acted on, where the effect was seen, and who reports it.
ataxia (Lynch et al. (2017): activation, acute dosing, central nervous system, cardiovascular; Bowes et al. (2012): activation, central nervous system)
muscle relaxation (Bowes et al. (2012): activation, central nervous system; Lynch et al. (2017): activation, acute dosing, central nervous system, cardiovascular)
abuse potential (activation; central nervous system; source: Bowes et al. (2012))
anterograde amnesia (activation; central nervous system; source: Bowes et al. (2012))
anticonvulsant (activation; central nervous system; source: Bowes et al. (2012))
anxiolysis (activation; central nervous system; source: Bowes et al. (2012))
convulsions (inhibition, acute dosing; central nervous system, cardiovascular; source: Lynch et al. (2017))
decreased anxiety (activation, acute dosing; central nervous system, cardiovascular; source: Lynch et al. (2017))
decreased blood pressure (activation, acute dosing; central nervous system, cardiovascular; source: Lynch et al. (2017))
decreased body temperature (activation, acute dosing; central nervous system, cardiovascular; source: Lynch et al. (2017))
decreased cardiac contractility (activation, acute dosing; central nervous system, cardiovascular; source: Lynch et al. (2017))
decreased convulsions (activation, acute dosing; central nervous system, cardiovascular; source: Lynch et al. (2017))
decreased locomotor activity (activation, acute dosing; central nervous system, cardiovascular; source: Lynch et al. (2017))
decreased memory (activation, acute dosing; central nervous system, cardiovascular; source: Lynch et al. (2017))
decreased pain (activation, acute dosing; central nervous system, cardiovascular; source: Lynch et al. (2017))
decreased sleep (inhibition, acute dosing; central nervous system, cardiovascular; source: Lynch et al. (2017))
depression (activation; central nervous system; source: Bowes et al. (2012))
dizziness (activation; central nervous system; source: Bowes et al. (2012))
drug abuse/dependence (activation, acute dosing; central nervous system, cardiovascular; source: Lynch et al. (2017))
increased cardiac output (activation, acute dosing; central nervous system, cardiovascular; source: Lynch et al. (2017))
increased eating (activation, acute dosing; central nervous system, cardiovascular; source: Lynch et al. (2017))
increased respiratory rate (activation, acute dosing; central nervous system, cardiovascular; source: Lynch et al. (2017))
increased sleep (activation, acute dosing; central nervous system, cardiovascular; source: Lynch et al. (2017))
sedation (activation; central nervous system; source: Bowes et al. (2012))
seizure (when used as a BZD antidote) (inhibition; central nervous system; source: Bowes et al. (2012))
Occurrence, Epileptic seizure (brain; source: AOP-Wiki)
Gene: Protein-coding gene on chromosome 5 (161,847,063 to 161,899,981, forward strand). Ensembl gene ENSG00000022355.
Subcellular location: Postsynaptic cell membrane; Cell membrane; Cytoplasmic vesicle membrane
Subcellular location (Human Protein Atlas): Plasma membrane; Nucleoplasm
Pathways (Reactome):
Neuronal System: GABA receptor activation
Signal Transduction: Signaling by ERBB4
Gene Ontology:
Molecular function: GABA-A receptor activity; GABA-gated chloride ion channel activity; GABA receptor activity; extracellular ligand-gated monoatomic ion channel activity; monoatomic ion channel activity; signaling receptor activity; transmembrane signaling receptor activity; transmitter-gated monoatomic ion channel activity involved in regulation of postsynaptic membrane potential
Biological process: chloride transmembrane transport; gamma-aminobutyric acid signaling pathway; inhibitory synapse assembly; synaptic transmission, GABAergic; extrasynaptic signaling via GABA; chloride transport; monoatomic ion transmembrane transport; monoatomic ion transport; regulation of postsynaptic membrane potential
Cellular component: dendritic spine; GABA-A receptor complex; plasma membrane; cytoplasmic vesicle membrane; dendrite membrane; GABA receptor complex; postsynapse; postsynaptic membrane; postsynaptic specialization membrane; GABA-ergic synapse; membrane
Genetic constraint (gnomAD): Loss-of-function variants: 5 observed, 37.34 expected, observed/expected ratio (o/e) 0.13, 90% interval 0.069 to 0.28. The upper end of that interval is the gene's LOEUF score, 0.28, which puts it in group 1 of 6, group 1 being the genes least tolerant of losing a copy. Missense variants: 256 observed, 523.82 expected, observed/expected ratio (o/e) 0.49, 90% interval 0.44 to 0.54. Synonymous variants: 192 observed, 188.75 expected, observed/expected ratio (o/e) 1.02, 90% interval 0.9 to 1.15.
Gene-disease validity (ClinGen):
ClinGen rates the evidence that GABRA1 causes each of these diseases.
epilepsy (autosomal dominant): Definitive. A brain disorder characterized by episodes of abnormally increased neuronal discharge resulting in transient episodes of sensory or motor neurological dysfunction, or psychic dysfunction.
Homologues: Orthologues: chimpanzee GABRA1 (100% identical), macaque GABRA1 (99% identical), dog GABRA1 (99% identical), guinea pig GABRA1 (98% identical), mouse Gabra1 (98% identical), pig GABRA1 (98% identical), rabbit GABRA1 (98% identical), rat Gabra1 (98% identical), tropical clawed frog gabra1 (89% identical), zebrafish gabra1 (85% identical). Paralogues in human: GABRA2 (75% identical), GABRA3 (71% identical), GABRA5 (70% identical), GABRA4 (59% identical), GABRA6 (57% identical), GABRG1 (44% identical), GABRG2 (43% identical), GABRG3 (42% identical), GLRA2 (36% identical), GLRA3 (35% identical), GABRE (35% identical), GABRB1 (34% identical), and 33 more.
Diseases named in the same sentence as GABRA1 in open-access papers:
GABRA1 is named in the same sentence as 88 diseases in open-access papers, as found by Europe PMC text mining. Sharing a sentence is not in itself a finding about the gene and the disease. The quoted sentences say what the papers report.
epilepsy (54 papers, 2011 to 2026). "FS are relatively common in GABAA receptor‐associated epilepsies caused by variants in GABRA1, GABRB3 or GABRG2." (PMID 37621067, 2024). "This study suggested that GABRA1 variants were potentially associated with a spectrum of epilepsies, including EFS+, DEE, and GTCA." (PMID 38269327, 2023). "De novo GABRA1 mutations were identified in six unrelated patients with heterogeneous epilepsy, including three missense mutations (p.His83Asn, p.Val207Phe, and p.Arg214Cys) and one frameshift mutation (p.Thr453Hisfs*47)." (PMID 38269327, 2023). "In conclusion, this study suggested that GABRA1 variants were potentially associated with a spectrum of epilepsies, including EFS+, DEE, and GTCA." (PMID 38269327, 2023). "This study suggested that GABRA1 is associated with a spectrum of epilepsies, including severe DEE, IGEs, and EFS+." (PMID 38269327, 2023). "During the last decade, with the candidate gene approach, only few epilepsy-associated genes were reported, such as GABRA1, SLC2A1, CACNA1H and EFHC1, of which the latter two remain debatable." (PMID 40217359, 2023). "Heterogeneous epilepsies were present in the six cases with GABRA1 mutations, including two with EFS+, three with DEE, and one with GTCA." (PMID 38269327, 2023). "De novo pathogenic variants in GABRA1 are more common than inherited pathogenic variants, and most epilepsy symptoms begin in the first year of life, manifesting with a variety of seizure types and developmental delays." (PMID 35937053, 2022). "In summary, de novo pathogenic variants in GABRA1 are more common than inherited pathogenic variants, and most epilepsy symptoms caused by GABRA1 begin in the first year of life." (PMID 35937053, 2022). "For the GABRA1 rs2279020 polymorphism, eight studies were included involving 1,688 patients with epilepsy and 1,233 controls." (PMID 36188399, 2022). "In nearly all patients with pathogenic GABRA1 variants, the clinical phenotypes include epilepsies within a spectrum of different severity, ranging from generalized epilepsies to severe epileptic encephalopathies." (PMID 35269865, 2022). "This mutation coincidentally occurs at the same residue as that of a previously reported GABRA1 variant T292I identified from a pediatric patient with severe epilepsy." (PMID 35269865, 2022). "This study aimed to summarize the clinical phenotype and genotype of children with epilepsy caused by GABRA1 gene variants." (PMID 35937053, 2022). "The currently known epilepsy-associated variants identified in GABAA receptor subunits are predominantly distributed in the four genes (GABRA1, GABRB2, GABRB3 and GABRG2) that code for the most commonly distributed receptor isoforms." (PMID 34095830, 2021). "Since then, rare coding variants GABAA receptor subtypes including GABRA1 have been associated with both benign and severe epileptic syndromes, in unspecified epilepsy and in GGE, although they remain very rare in terms of frequency." (PMID 31611775, 2019). "Variants in GABRA1 have been associated with different epilepsies ranging from mild generalized forms to epileptic encephalopathies." (PMID 31568673, 2019). "We identified a de novo GABRA1 pathogenic variant (R214C) in a patient with EE, treatment-resistant epilepsy, intellectual disability and autism." (PMID 31707987, 2019). "Mutations in the GABRA1 gene are linked to a spectrum of endophenotypes of GGE syndromes as well as more severe forms of epilepsy associated with intellectual disability." (PMID 25352779, 2014). "This mouse model recapitulates some of the epilepsy phenotypes that were reported in human carriers of GABRA1 mutations." (PMID 25352779, 2014). "Several monogenic epilepsies may result from mutations in the GABRA1, GABRB3, and GABRG2 genes encoding for the predominant α1β3γ2 GABAA isoforms." (PMID 38003469, 2023). "Mutation of the GABRA1 gene is associated with neurodevelopmental defects and epilepsy." (PMID 36747751, 2023).
epilepsy (continued). "Hrd1 is mechanistically linked to neurological disorders presenting with seizures: Hrd1, which is expressed in neurons in many regions of the brain, is involved in the degradation of epilepsy-causing mutant GABRA1 and the mutant neuroserpin responsible for FENIB." (PMID 35327449, 2022). "In the eight patients with epilepsy, all GABRA1 gene variants were heterozygous." (PMID 35937053, 2022). "Within this study, GABRA1 gene pathogenic variants were characterized by using whole exome sequencing technology in eight children with epilepsy, and gene phenotypes were combined with clinical manifestations to develop a new direction for clinical diagnosis and treatment." (PMID 35937053, 2022). "This suggests that GABRA1 IVS11 + 15 A>G intronic polymorphism may be involved in the drug response in epilepsy patients." (PMID 21747585, 2011). "Our findings revealed that these frameshift variants of GABRA1 utilize overlapping yet distinct molecular mechanisms to impair proteostasis, providing insights into the pathogenesis of GABAAR-associated epilepsy." (PMID 39651292, 2025). "The first reports of epilepsy‐associated de novo variants included variants within the GABAA receptor subunit encoding genes, GABRA1 and GABRB3." (PMID 37621067, 2024). "Overall, the Gabra1 mutant mouse model is a valuable tool for investigating the role of GABAA receptors in epilepsy and understanding how impaired inhibitory signaling contributes to seizure disorders." (PMID 39452036, 2024). "Mutations in specific genes such as GABRA1, GRIN2A, and CACNG2 have been associated with different types of epilepsy, providing valuable models for understanding how these genetic alterations affect neuronal function and trigger epileptic seizures." (PMID 39452036, 2024). "In the present study, we aim to find the association of SNPs in three genes including SCN1A, GABRA1 and ABCB1 in Vietnamese children affected by epilepsy." (PMID 38674283, 2024). "We aimed to examine the relationship between SCN1A, GABRA1 and ABCB1 polymorphism and drug response in epilepsy children in Vietnam." (PMID 38674283, 2024). "We aimed to assess the association of GABRA1 rs2279020 and GABRA6 rs3219151 with epilepsy risk using a meta-analysis." (PMID 36188399, 2022). "Indeed, increasing numbers of GABRA1 variants have been implicated in causing haploinsufficiency and loss of function of the GABAARs, thereby causally contributing to the pathogenesis of various forms of epilepsy, Dravet Syndrome, early-onset EEs, and developmental delay." (PMID 35269865, 2022). "The five newly discovered pathogenic variants which enrich the GABRA1 gene pathogenic variant spectrum include case 1 with West syndrome, case 3 with GEFS+, case 4 with FS, case 2 and 5 with uncertain epilepsy." (PMID 35937053, 2022). "We therefore identified miR‐129–2‐3p as a novel seizure regulator and characterized the miR‐129–2‐3p/GABRA1 pathway as a potential target in the prevention and treatment of epilepsy." (PMID 34029007, 2021). "To study the potential involvement of miR‐129–2‐3p and GABRA1 in epilepsy, we generated an animal model of epilepsy by unilateral i.c.v. injection of KA into the SD rat brain." (PMID 34029007, 2021). "It is well known that mutations/variants in GABRA1, GABRB2, GABRB3, or GABRG2 produce several different types of epilepsy." (PMID 34095830, 2021). "The effects of targeting miR‐129–2‐3p and GABRA1 on epilepsy were assessed by electroencephalography (EEG) and immunostaining." (PMID 34029007, 2021). "GABRA1‐related epileptic disorders have been shown to encompass a broad clinical spectrum spanning from mild generalized epilepsies to severe infantile DEE." (PMID 31568673, 2019).